RN7SKP160 (RN7SK pseudogene 160)
Gene: Miscellaneous RNA gene on chromosome 1 (173,791,548 to 173,791,887, forward strand). Ensembl gene ENSG00000200674.
Homologues: Orthologues: chimpanzee 7SK (97% identical), zebrafish rn7sk (79% identical). Paralogues in human: 7SK (77% identical), RN7SKP185 (73% identical), RN7SKP227 (73% identical), RN7SKP187 (72% identical), RN7SKP118 (71% identical), RN7SKP174 (71% identical), RN7SKP48 (70% identical), RN7SKP203 (70% identical), RN7SKP62 (70% identical), RN7SKP178 (70% identical), RN7SKP76 (69% identical), RN7SKP80 (69% identical), and 283 more.